CXCR2 (C-X-C motif chemokine receptor 2)
Diseases named in the same sentence as CXCR2 in open-access papers (continued):
Sharing a sentence is not in itself a finding about the gene and the disease.
lymph node metastasis (10 papers, 2015 to 2023). "Notably, CXCR2/IL8 activation is associated with both NSCLC lymph node metastasis and unfavorable prognosis for patients with NSCLC." (PMID 36769365, 2023). "A multivariate logistic regression analysis revealed that CXCR2 expression (p = 0.031) and lymph node metastasis (p = 0.004) were significantly correlated with the CCA patients’ overall survival." (PMID 35377900, 2022). "The univariate analysis revealed that the overall survival of the patients was significantly correlated with CXCR2 expression in cancer cells, high age (≥70 years), T invasion (T2–T4), lymph node metastasis, and distant metastasis." (PMID 35377900, 2022). "The multivariate logistic regression analysis revealed that CXCR2 expression (p = 0.031) and lymph node metastasis (p = 0.004) were significantly correlated with the CCA patients’ overall survival." (PMID 35377900, 2022). "Clinical data indicated that CXCL8 expression was significantly correlated with disease-free survival (DFS), lymph node metastasis, high expression levels of CXCR2, and high infiltration of an increased number of CD204-positive macrophages." (PMID 33390169, 2021). "Comparative analysis of the CXC chemokine/receptor genes revealed significantly higher expression levels of genes encoding ELR+ CXC chemokines/receptors (CXCL1, CXCL3, CXCL6, CXCR1, and CXCR2) in bone metastases relative to lymph node metastases." (PMID 33195424, 2020). "Indeed, CXCR2 is highly expressed in ESCC patients and is significantly associated with lymph node metastasis and a reduced overall survival rate." (PMID 33390169, 2021). "Opposite results were obtained using the immunohistochemical method, where the authors demonstrated that the increased expression of both CXCL-8 and CXCR-2 correlated with the depth of invasion, lymph node metastasis, pathological stage, lymphatic and venous invasion." (PMID 30820705, 2019). "CXCL8 and its receptor CXCR2 (IL-8 Receptor, beta) are overexpressed in ESCC, and their level correlates with lymphatic invasion, venous invasion, lymph node metastasis, depth of invasion, and poor prognosis." (PMID 33390169, 2021). "We found that a high expression of CXCL8 was closely correlated with lymph node metastasis (p = 0.039), a high number of infiltrating CD204-positive macrophages (p = 0.043), and a high expression level of CXCR2 (p = 0.043)." (PMID 29285315, 2017). "A depth of tumor invasion of pT2 or greater, lymph node metastasis, a disease stage of pStage IIA or greater, lymphatic invasion, venous invasion, and CXCR2(+)/complication(+) status were identified as predictive markers of RFS." (PMID 26231560, 2015). "Notably, the preoperative PSA concentration, clinical tumor stage, and primary Gleason score were identified as significant predictors of lymph node metastasis, as were all evaluated CXC chemokine/receptors, with the exceptions of CXCR2 and CXCL8." (PMID 33195424, 2020).
metastatic disease (10 papers, 2012 to 2025). "First, considering our findings in the in vitro assays and human IDCs, the tumor cells that expressed hPTTG1 and CXCR2 at high levels in both primary and metastatic tumors may escape senescence via the loss of p21 expression." (PMID 22789011, 2012). "Considering the predominant role of IL‐8–CXCR1/CXCR2 in NETosis, various clinical trials are presently underway intending to determine the efficacy of CXCR1/CXCR2 inhibitors in blocking NETs and controlling metastatic disease treatments." (PMID 39015554, 2024). "Furthermore, CXCR2+ immune cells were more abundant in stroma-rich primary and metastatic tumor tissues, suggesting a role for the CXCL8/CXCR2 axis in promoting an unfavorable tumor phenotype and supporting immunosuppression." (PMID 40943634, 2025). "The unexpected therapeutic effects of CXCR2 CAR-T in the PDAC liver metastasis model may be due to the more exposed recognition of CXCL5 in metastatic tumors compared to the shielding of the stroma structure in primary tumors." (PMID 38430267, 2024). "CXCL5/CXCR2 pathway facilitates the development of metastatic disease in other cancers." (PMID 36968223, 2023). "The role of CXCR2 in promoting metastasis alongside the evidence of elevated CXCR2 in metastatic disease compared to localized disease may suggest that patients with metastatic disease will benefit from a combination of immunotherapy and CXCR2 antagonism." (PMID 34944914, 2021). "Furthermore, given the role of CXCR2 in maintaining the metastatic niche, CXCR2 antagonists may be particularly useful in patients with late-stage or metastatic disease." (PMID 34944914, 2021). "The higher number of macrophages and augmented expression of IL-1α and CXC chemokines in highly metastatic tumors versus lower metastatic tumors led us to examine whether IL-1/IL-1R and/or CXC chemokines/CXCR2 were involved in the ability of LNM35 cells to recruit macrophages." (PMID 24924428, 2014).
osteosarcoma (10 papers, 2019 to 2025). A usually aggressive malignant bone-forming mesenchymal neoplasm, predominantly affecting adolescents and young adults. "Here, the association between CXC chemokine receptors (CXCR2–5) and prognosis in osteosarcoma was studied." (PMID 31696204, 2019). "This activation of CXCR2 on a cancer cell in the blood is associated with an increase in vascular cell adhesion molecule-1 (VCAM-1) expression on cells with activated CXCR2, something that has been observed in the metastasis to the lung by osteosarcoma." (PMID 35216283, 2022). "The result of the study firmly indicates that the CXCL1/CXCR2 is an essential axis for metastasis of osteosarcoma." (PMID 34760697, 2021). "Our investigation suggests that CXCL1/CXCR2, as a therapeutic candidate, can be targeted to further develop medicine to suppress or prevent the metastatic spread of osteosarcoma." (PMID 34760697, 2021). "Recently, CXCL1 and CXCR2 have been crucial indicators for lung metastasis in osteosarcoma by paracrine releases, suggesting the involvement of directing neutrophils into tumor microenvironment." (PMID 34760697, 2021). "We examined the levels of CXCR2 in osteosarcoma cells by immunofluorescence, Western blotting and flow cytometry." (PMID 32079335, 2020). "Immunohistochemistry staining of clinical osteosarcoma specimens revealed positive correlations between CXCR2 expression and pathology stage and also vascular cell adhesion molecule 1 (VCAM-1) expression." (PMID 32079335, 2020). "We next examined levels of CXCR2 expression in osteosarcoma specimens, to determine the prognostic relevance of CXCR2 in osteosarcoma progression." (PMID 32079335, 2020). "We found that VCAM-1 expression increased with tumor stage and was positively correlated with CXCR2 expression in osteosarcoma specimens." (PMID 32079335, 2020). "This evidence suggests that the CXCL1/CXCR2 axis plays a pivotal role in osteosarcoma lung metastasis." (PMID 32079335, 2020). "The paracrine CXCL1/CXCR2 network links HPAECs and osteosarcoma cells, provides a metastatic trace for the cells, and directs their destination." (PMID 32079335, 2020). "We are the first to provide evidence showing that HPAECs-induced secretion of CXCL1 recruits CXCR2-expressing osteosarcoma cells to pre-metastatic pulmonary sites." (PMID 32079335, 2020). "As osteosarcoma cells contain high levels of CXCR2, a chemokine receptor of CXCL1, their response to HPAECs secretion of CXCL1 promotes lung metastasis." (PMID 32079335, 2020). "As expected, osteosarcoma cell lines expressed CXCR2 and expression levels were positively correlated with anchorage-independent growth ability, as described in a previous report." (PMID 32079335, 2020). "The clinical data from a total of 98 cases with osteosarcoma and the corresponding expression data of CXCR2, CXCR3, CXCR4, and CXCR5 were included." (PMID 31696204, 2019). "Based on the available data of CXCRs in osteosarcoma, we assessed the prognostic role of CXCR2, CXCR4, and CXCR5 expression in osteosarcoma." (PMID 31696204, 2019). "CXCR2 expression was also determined in osteosarcoma cell lines and normal osteoblast cells." (PMID 32079335, 2020). "Here, we show that the CXCL1/CXCR2 paracrine axis is crucial for lung metastasis in osteosarcoma." (PMID 32079335, 2020). "To determine whether the CXCL1/CXCR2 axis is involved in osteosarcoma lung metastasis, we examined the expression of CXCL1 in human pulmonary artery endothelial cells (HPAECs), which reside in pulmonary vasculature, where metastatic foci are found." (PMID 32079335, 2020). "In osteosarcoma, CXCL1 is known to upregulate the expression of NF-κB via the CXCR2/FAK/PI3K/Akt pathway." (PMID 36614235, 2023). "Our findings demonstrate the cascade mechanism regulating the network in lung metastasis osteosarcoma, therefore indicating that the CXCL1/CXCR2 pathway is a worthwhile candidate to further develop treatment schemas." (PMID 34760697, 2021).
osteosarcoma (continued). "Our results suggested that CXCL1 via the CXCR2/FAK/PI3K/Akt/NF-κB pathway enhanced VCAM-1 expression to assist the migratory and invasive activity in osteosarcoma cells." (PMID 34760697, 2021). "Our findings illustrate a molecular mechanism of lung metastasis in osteosarcoma and indicate that CXCL1/CXCR2 is worth targeting in treatment schemas." (PMID 32079335, 2020). "Pretreatment with pathway inhibitors, including CXCR2, FAK, PI3K, and Akt, strongly inhibited NF-κB reporter activity in osteosarcoma cells incubated with HPAECs CM." (PMID 32079335, 2020). "The Kaplan–Meier analyses were conducted to estimate the survival impact of expression of CXCR2, CXCR3, CXCR4, and CXCR5 in osteosarcoma." (PMID 31696204, 2019). "In consideration of the fact that HPAECs-secreted CXCL1 recruits osteosarcoma cells and contributes to lung metastasis, and our findings showing that VCAM-1 expression is positively correlated with CXCR2 in osteosarcoma tissue, we analyzed VCAM-1 expression after HPAECs CM treatment." (PMID 32079335, 2020). "To validate whether HPAECs-secreted CXCL1 plays a major role in osteosarcoma homing and migration, we used CXCL1 neutralizing antibody to block the CXCL1/CXCR2 interaction between HPAECs and osteosarcoma cells." (PMID 32079335, 2020). "Finally, the CXCR2 chemical inhibitor SB225002 and CXCR2 shRNA confirmed that the CXCL1/CXCR2 axis is required for VCAM-1 expression and mobility of osteosarcoma cells." (PMID 32079335, 2020). "Thus, CXCR2 expression correlates with VCAM-1 expression and tumor progression in osteosarcoma." (PMID 32079335, 2020). "CXCR2 expression was higher in osteosarcoma cell lines than in normal osteoblast cells." (PMID 32079335, 2020). "The current study showed that the CXCL1 could signal the CXCR2/focal adhesion kinase (FAK)/phosphatidylinositol-3-kinase (PI3K)/Akt/nuclear factor-kappa B (NF-κB) pathway to increase VCAM-1 expression and subsequently upregulate the metastasis ability of human osteosarcoma cells." (PMID 34760697, 2021). "In the present study, we observed that the expression of CXCR2, CXCR4, and CXCR5 were not correlated with the prognosis, but CXCR3 low expression was correlated with poor prognosis in osteosarcoma." (PMID 31696204, 2019).
periodontitis (10 papers, 2011 to 2026). An acute or chronic inflammatory process that affects the tissues that surround and support the teeth. "Genetic variants in a chemokine receptor Interleukin 8 receptor, beta (CXCR2) have also been associated with susceptibility to prolonged periodontal bacteremia leading to chronic periodontitis." (PMID 39337647, 2024). "This study did not confirm any significant association between the investigated SNPs in the CXCR2 gene and chronic periodontitis." (PMID 30863202, 2019). "Same conditions of periodontitis and periodontal bone loss are observed in CXCR2-deficient mice, which cannot recruit neutrophils to oral tissues and develop severe bone loss early in life." (PMID 27019855, 2016). "Previous studies of our group found association of haplotypes in the IL8 and in the CXCR2 genes with the multifactorial disease chronic periodontitis." (PMID 22051099, 2011). "Different basal levels of IL-8 could be due to present, even small, sources of inflammation, such as periodontitis, or could be due to genetic factors, such as polymorphisms in genes related to IL-8 and CXCR2." (PMID 38654913, 2023). "To further investigate the essential function of neutrophils in the exacerbation of COPD, we blocked the recruitment of neutrophils in COPD combined with periodontitis model (Ctrl) using CXCL2 receptor CXCR2 antagonist (Treatment)." (PMID 41507139, 2026). "The application of an antagonist targeting the critical ligand CXCR2 to block neutrophils recruitment reversed the progression of COPD aggravated by periodontitis, indicating the promotion of COPD by periodontal pathogens mainly through neutrophils." (PMID 41507139, 2026). "In white non-smokers, the C-T-G/T-C-A haplotype for the CXCR2 rs2230054-rs1126579-rs1126580 polymorphisms correlated with an increased susceptibility to periodontitis, while the C-T-G/T-C-G haplotype protected against the disease." (PMID 38001676, 2023). "Similar findings of altered IL-23 and IL-17 responses were also reported in the chemokine receptor CXCR2-deficient mice, which do not recruit neutrophils to periodontal tissues and have susceptibility to periodontitis." (PMID 27019855, 2016). "The first aim of this study was to investigate the CXCR2 gene variability in chronic periodontitis (CP) patients and healthy nonperiodontitis controls in the Czech population." (PMID 30863202, 2019).
acute myeloid leukemia (9 papers, 2016 to 2025). Acute myeloid leukemia (AML) is a group of neoplasms arising from precursor cells committed to the myeloid cell-line differentiation. "In acute myeloid leukemia, IL-8 and CXCR2 were found to be overexpressed in stem and progenitor cells, and targeting CXCR2 reduced the viability of leukemic stem cells." (PMID 27348007, 2016). "Nevertheless, CXCR2 expression was augmented in patients with acute myeloid leukemia (LAML)." (PMID 34692853, 2021). "The CXCL5-Fc and CXCL1-Fc fusion proteins showed greater binding than the native chemokines to THP-1 cells, which are acute myeloid leukemia (AML) cells of myeloid origin and CXCR2-positive." (PMID 40427538, 2025).
bronchiectasis (9 papers, 2011 to 2024). Segmental, irreversible dilation of the bronchial tree resulting in the accumulation of secretions which leads to obstruction. "SB-656933, a receptor antagonist for CXCR2, has been tested in patients with CF bronchiectasis and was shown to be well-tolerated (except minor reports of headaches) with improvements in sputum neutrophils but no improvement in symptoms or lung function." (PMID 30380761, 2018). "We detected reduced levels of the chemokine receptors CXCR1 and CXCR2 and an increased expression of the chemokine receptor CXCR4 on sputum neutrophils as compared to peripheral blood neutrophils, both in PCD and in bronchiectasis." (PMID 36528664, 2022).
cardiac hypertrophy (9 papers, 2021 to 2025). "In angiotensin II-induced cardiac atrial fibrillation animal model, CXCR2 has also been proved to participate in immune cells infiltration and mediates cardiac hypertrophy and remodeling through regulation of monocyte." (PMID 35305619, 2022). "CXCR2 antagonist relieved UA-induced cardiac hypertrophy and suppressed cardiac inflammation and fibrosis." (PMID 34385934, 2021). "Elevated CXCL1 is responsible for attracting CXCR2+ macrophages, leading to ventricular hypertrophy." (PMID 34385934, 2021). "It is reported that CXCL1/CXCR2 axis mediates Ang II-induced cardiac hypertrophy and remodeling." (PMID 33869197, 2021). "CXCR2 blockade therapy also ameliorates Ang II‐induced cardiac injury, indicating that therapies targeting inflammatory cytokines and chemokines could effectively treat Ang II‐induced cardiac hypertrophy." (PMID 40682481, 2025). "Thus, the interventions against CXCL1/CXCR2 may be effective for the prevention and treatment of UA-induced cardiac hypertrophy and inflammatory responses." (PMID 34385934, 2021).
cholangiocarcinoma (9 papers, 2018 to 2025). A carcinoma that arises from the intrahepatic biliary tree (intrahepatic cholangiocarcinoma) or from the junction, or adjacent to the junction, of the right and left hepatic ducts (hilar cholangiocarcinoma). "Higher CXCR2 expression is also associated with a better prognosis for patients with cholangiocarcinoma." (PMID 37408240, 2023). "Recent studies have shown that CXCR2 can be used as a valuable independent prognostic marker in patients with cholangiocarcinoma, and its mediated immune response may have a tumor inhibition effect on cholangiocarcinoma cells." (PMID 36401283, 2022). "The CXCL5/CXCR2 axis promotes lymphangiogenesis, epithelial–mesenchymal transition (EMT), and matrix metalloproteinase (MMP) upregulation in cholangiocarcinoma (CCA)." (PMID 40564091, 2025).
diffuse large B-cell lymphoma (9 papers, 2021 to 2025). "Considering the CXCR2 rs1126580 polymorphism, its involvement has also been reported in several cancer types, including diffuse large B-cell lymphoma (DLBCL), bile duct cancer, and classic Kaposi sarcoma (CKS)." (PMID 38001676, 2023). "In the prior research, it was found that through the interaction with CXCR2 on neutrophils, IL-8 derived from diffuse large B-cell lymphoma (DLBCL) can form NETs via the Src, p38, and ERK signaling pathways." (PMID 40148973, 2025). "NETs induced by tumor-derived CXCL8 coupled with CXCR2 promoted diffuse large B-cell lymphoma (DLBCL) progression by activating Toll-like receptor 9 (TLR9), an important DNA sensor, and its downstream pathways." (PMID 37198402, 2023). "The role of CXCR2 in the activation of NETosis was confirmed in atherosclerosis (AS), as well as diffuse large B-cell lymphoma (DLBCL)." (PMID 34804066, 2021). "In diffuse large B-cell lymphoma (DLBCL), IL-8 secreted by tumor cells binds to its receptor, CXCR2, on neutrophils, promoting NET formation." (PMID 40365275, 2025). "In patients with diffuse large B-cell lymphoma (DLBCL), DLBCL-derived IL8 interacting with CXCR2 on neutrophils resulted in NET formation via Src, p38 and ERK signalling." (PMID 36618417, 2022).